EGFR (epidermal growth factor receptor)
Diseases named in the same sentence as EGFR in open-access papers (continued):
Sharing a sentence is not in itself a finding about the gene and the disease.
breast carcinoma (continued). "Furthermore, the co-expression of gelsolin with erb-B2 and epidermal growth factor receptor (EGFR) is a predictor of poor prognosis in breast cancer." (PMID 22927998, 2012). "Thus, it was shown that BSMS1 markedly activates both miR-146a and miR-146b expression in breast carcinoma cells and, through this mechanism, inhibits EGFR expression, thus leading to a reduced metastatic potential of these cells." (PMID 22453030, 2012). "The increase in EGFR, Src and AnxA2 levels upon Her-2 downregulation and inhibition led us to investigate the role of AnxA2 in EGFR signaling in TNBC subset of breast cancer, where EGFR plays a major role in survival, growth, migration and invasion of cancer cells." (PMID 22957061, 2012). "Additionally, aberrant EGFR signaling is a major characteristic of a human cancer including breast cancer." (PMID 22905152, 2012). "P/AON/2C5 also efficiently inhibited EGFR expression in both breast cancer cell lines." (PMID 22355336, 2012). "More recently, the EGFR-selective tyrosine kinase inhibitor gefitinib has been shown to inhibit the growth of EGFR-positive MCF-7-derived tamoxifen-resistant breast cancer cells, an effect that can be abrogated by exposing the cells to non-EGF ligands such as heregulin-β and IGF-II." (PMID 22545054, 2012). "Adding exogenous HGF to these breast cancer cell lines decreased sensitivity to EGFR TKIs." (PMID 22788954, 2012). "EGFR plays a major role in aggressive breast cancers, including IBC." (PMID 22570721, 2012). "Thus in our studies, we aimed to determine the effect of EBP50 expression on EGF-induced cell proliferation and activation of EGFR signaling in the breast cancer cell lines, MDA-MB-231 and MCF-7." (PMID 22476347, 2012). "However wild-type KRAS is significantly activated in breast cancers that over-express EGFR and ErbB2." (PMID 22701724, 2012). "In addition, the dual inhibition of the focal adhesion and EGFR signaling pathways can cooperatively enhance apoptosis in breast cancers." (PMID 22346740, 2012). "Overexpression of TFPI in breast cancer cells affected the expression of mRNAs and miRNAs involved in processes facilitating cancer cell growth and immunologic response, possibly by signal transduction involving the EGFR pathway." (PMID 23071754, 2012). "Therefore, the goal of this study was to further elucidate the role of EBP50 on EGF-induced breast cancer cell proliferation and EGFR signaling in breast cancer cells." (PMID 22476347, 2012). "Breast cancers appear to be intrinsically resistant to EGFR TKIs and therefore may regulate Met via a distinct mechanism." (PMID 22788954, 2012). "In summary, this study demonstrated that EBP50 expression could inhibit EGF-induced breast cancer cell proliferation by blocking EGFR phosphorylation and its downstream signaling." (PMID 22476347, 2012). "Autocrine activation of EGFR on breast cancer cells may also influence signaling with the bone microenvironment." (PMID 22276166, 2012). "In addition, Zhang and colleagues used a novel mouse model to demonstrate that HGF expression can promote tumor growth of EGFR-expressing breast cancers." (PMID 22788954, 2012). "Commonly used protein biomarkers of breast cancer, including proteins from HER2, uPA/PAI-1 and EGFR signaling pathways showed higher than previously reported intratumoral heterogeneity of expression levels both within primary breast cancers and between lymph node metastases from the same patient." (PMID 22792263, 2012). "Our current study also indicated EGFR inhibition in breast cancer cells by PEITC treatment." (PMID 22824293, 2012). "Indeed ErbB3 mRNA levels relative to normal gland and measured by real-time PCR are increased in 46% of breast cancers and correlate positively with those for ErbB4 and negatively with EGFR mRNA." (PMID 22889873, 2012).
breast carcinoma (continued). "Tumors of this subtype have a high expression of basal markers, some of which (such as EGFR) may interact with T cell-mediated immune response to affect clinical outcome in breast cancer." (PMID 22420471, 2012). "Recent evidence shows that EGFR may play a significant role in some HGF/Met mediated biological responses of mammary tumor and epithelial cells." (PMID 23028720, 2012). "Its expression is found in myoepithelial cells of normal mammary glands; therefore, it has been considered to be a myoepithelial marker, but its correlation with basal markers, such as CK5/6, CK14 and epidermal growth factor receptor (EGFR), in breast cancers remains to be solved." (PMID 21496280, 2011). "We obtained both FISH and RT-PCR EGFR data on 139 female patients with breast cancer." (PMID 22132735, 2011). "First, we examined the basal expression level of EGFR in a subset of breast cancer cell lines." (PMID 21813027, 2011). "Over-expression of EGFR/HER2 and downregulation of ER are molecular markers associated with de novo and acquired resistance to endocrine therapy in both pre-clinical models of breast cancer and in clinical studies." (PMID 21119660, 2011). "Moreover, this pathway is activated by VEGFR2 in endothelial cells and by EGFR in breast cancer cells, both of which are receptor tyrosine kinases." (PMID 21858086, 2011). "This was subsequently confirmed by the analysis of a gene expression microarray of 30 breast cancer cell lines, in which high mRNA expression of cPLA2α correlated with high EGFR expression and with the HER2-positive and basal-like subtypes of breast cancer in cell lines showing basal phenotype." (PMID 21119660, 2011). "In a different study, although the addition of this compound to MCF-7 breast cancer cells in vitro resulted in minimal growth inhibition, when combined with the dual EGFR/HER2 tyrosine kinase inhibitor, GW2974 (Sigma Aldrich), synergistic growth inhibition was observed." (PMID 21906355, 2011). "While it has previously been reported that cell surface EGFR promotes cell growth, and that internalization of the EGFR induces cell death in breast cancer cells, our present findings suggest that cell surface EGFR retained after Y27632 treatment exerts pro-proliferative signals." (PMID 21722395, 2011). "Our data so far indicates that GPR54 transactivates EGFR to regulate breast cancer cell invasion." (PMID 21738726, 2011). "Both of these invasive breast cancer cell lines exhibit basal EGFR phosphorylation." (PMID 21738726, 2011). "In agreement with the phenomenon observed in sarcoma cells, Pierce and colleagues showed that knocking down of MGAT5 expression, which led to decreased synthesis of galectin-3 ligands in molecules such as the EGFR, interfered with the migratory response of breast cancer cells in response to EGF." (PMID 22216245, 2011). "It will be of significant interest to investigate whether EGFR gene copy number is a suitable screening test for EGFR-targeted therapy for breast cancer." (PMID 22132735, 2011). "In addition, the overexpression of EGFR and erb-B2 oncogenes stimulates invasiveness of breast cancer cells." (PMID 22174624, 2011). "It has been in fact reported that treatment with the demethylating agent decitabine may result in the re-expression of EGFR in two breast cancer cell lines, in which EGFR transcription was abolished by EGFR promoter hypermethylation." (PMID 21559018, 2011). "The high frequency of EGFR expression in TNBCs suggests that loss of BRCA1 may be coupled, either directly or indirectly, with EGFR overexpression in breast cancer." (PMID 21396117, 2011). "In this current study we used FISH to detect EGFR gene copy numbers in breast carcinomas." (PMID 22132735, 2011). "Overexpression of EGFR protein occurs in 16–36% of breast cancers." (PMID 21980430, 2011). "EGFR is often strongly expressed in many cancers, including breast cancer." (PMID 22152097, 2011).
breast carcinoma (continued). "We identified EGFR gene amplification in 46 (33.1%) of the 139 patients with breast cancer." (PMID 22132735, 2011). "Therefore, aptamers were assayed for their ability to bind to both A431 epidermoid carcinoma cells (1–3 million EGFR molecules per cell) and MDA-MB-435 breast cancer cells (EGFR deficient)." (PMID 21687663, 2011). "Similar preclinical findings have also been reported for the pure anti-ER fulvestrant, and recent clinical studies examining cotargeting ER and EGFR and/or ErbB2 signalling pathways have reported improved response to a range of endocrine therapies in breast cancer patients." (PMID 21396094, 2011). "Several data sets regarding EGFR gene amplification in breast cancer are accessible." (PMID 22132735, 2011). "While the accumulating data just described show that IGF-1R operates through signaling cross-talk with estrogen-ER signaling and EGFR/HER2 regulatory pathways in antiestrogen-resistant breast cancer cells, the ER-independent role of IGF-1R signaling in antiestrogen resistance is poorly understood." (PMID 21595894, 2011). "The dual roles of G3 in modulating breast cancer cell resistance to chemotherapeutic agents may in part explain a potential mechanism for breast cancer cell resistance to chemotherapy and EGFR therapy." (PMID 22096483, 2011). "FRI approaches were first described in 1999 and then successfully used to study epidermal growth factor receptor (EGFR) labeled with Cy5.5 in breast tumors, tumor protease activity of breast carcinoma, protease activity in arthritis, osteoblast activity in vertebra and GFP expressing tumors in mice." (PMID 24310495, 2011). "This suggested that EGFR mutation analysis is not useful as a screening test for sensitivity to anti-EGFR therapy for breast cancers." (PMID 22132735, 2011). "It is important to study whether EGFR is overexpressed in patients with breast cancer since these patients can be given specific EGFR molecule tyrosine kinase inhibitors such as gefitinib and lapatinib." (PMID 22132735, 2011). "It has been suggested from breast cancer studies that lapatinib acts only on the phosphorylated form of EGFR (in the presence of wild-type ras/raf) which would mean that the number of patients potentially able to benefit represents at best 20% of the total population." (PMID 22091418, 2011). "It appears that positive EGFR protein overexpression could predict gene amplification in breast cancers." (PMID 22132735, 2011). "Our results are in agreement with previous studies demonstrating the lack of EGFR-activating mutations in breast cancer." (PMID 21730982, 2011). "Individuals with overexpression of versican in breast cancer may more likely benefit from anti-EGFR therapy given known effects of EGF-like motifs in versican, a scientific consideration that warrants further evaluation." (PMID 22096483, 2011). "It is known that EGFR gene amplification indicates EGF-sensitive breast cancer." (PMID 22132735, 2011). "EGFR signaling is essential for EF-directed migration of breast cancer cells." (PMID 21998723, 2011). "Thus, treating breast cancer patients with an EGFR inhibitor and β-blocker is recommended because the β-blocker can reduce tumor proliferation and metastasis; thus, increasing the probability of a optimistic prognosis." (PMID 21476970, 2011). "Thus, our results show for the first time that Kp-10 signaling via endogenous GPR54 leads to the transactivation of endogenous EGFR in breast cancer cells." (PMID 21738726, 2011). "Further studies showed that in breast cancers, Wnt1 transactivates EGFR, implying that constitutive Wnt signaling might impact not only the canonical pathway but also EGFR activity by augmenting ligand availability." (PMID 20828404, 2010).
breast carcinoma (continued). "Given the frequency at which abnormalities in EGFR signaling are present in human breast cancer and observations of how these changes influence tumor cell survival, migration, metastasis, and angiogenesis, EGFR has been an attractive target for therapeutic manipulation." (PMID 21079779, 2010). "According to our results, EGFR may have different effect on the progression of breast cancer of TA2 mice and human beings." (PMID 20092659, 2010). "We used two basal markers (CK5/6, EGFR) in accordance with the Carolina Breast Cancer Study." (PMID 20860845, 2010). "In addition, SP1 is a potent transactivator of IGF-IR and EGFR, two prominent genes overexpressed in breast cancer cells (for example, MDA-MB-468) and both of which were identified as hits in our screen." (PMID 20576088, 2010). "We have previously shown that constitutive phosphorylation of Met contributes to EGFR TKI resistance in breast cancer and that decreasing Met kinase activity, decreased EGFR tyrosine phosphorylation and proliferation in the presence of an EGFR tyrosine kinase inhibitor." (PMID 20624308, 2010). "In breast cancers, Wnt overexpression activates signaling via EGFR." (PMID 20828404, 2010). "In breast cancers, upregulation of Wnt-1 induces EGFR and Erk 1/2 MAPK activation." (PMID 20828404, 2010). "In addition, we have analyzed multiple autopsy samples from six cases that had a primary breast cancer, and found additional EGFR and PIK3CA mutations in breast cancers that metastasized to various sites including the brain." (PMID 20604919, 2010). "This study utilised the phospho-EGFR Tyr 1086 antibody in breast cancers and reported a lack of association with EGFR, as was also found in our colorectal cancers and has been reported in other epithelial malignancies." (PMID 19997103, 2010). "Dasatinib inhibits growth of breast cancer cells by modulating EGFR signaling." (PMID 20955590, 2010). "Our findings are similar to a study in high-risk breast cancer patients where EGFR, but not phospho-EGFR, was an adverse prognostic factor." (PMID 19997103, 2010). "Our results show that EGFR expression is correlated to PIPKIγ expression in breast cancer cells, which hints that EGFR and PIPKIγ may cooperate to facilitate breast cancer metastasis." (PMID 20074374, 2010). "Members of the EGFR gene family have been targets of molecular therapy for breast cancer." (PMID 21080969, 2010). "On average, 50% to 70% of lung, colon and breast cancers have EGFR and ErbB3 overexpression." (PMID 20828404, 2010). "Inhibitors were used to test whether versican G3 activated breast cancer cell proliferation through EGFR-mediated signaling." (PMID 21079779, 2010). "Therefore, the abrogation of the kinase activity of each molecule in combination provides intriguing evidence for dual EGFR and Met inhibitor studies in breast cancers." (PMID 20624308, 2010). "In the present study, expression profiles data showed that EGFR expression was down-regulated in cancer tissues compared with that of the matched mammary glands, in contrast to results previously reported for human breast cancer." (PMID 20092659, 2010). "As we know, EGFR is one of the prognostic factors and therapeutic targets for human breast cancers." (PMID 20092659, 2010). "Assessment of the mutation status of KRAS might also be of potential relevance in other EGFR-overexpressing tumors, such as those occurring in breast cancer." (PMID 20385028, 2010). "Versican G3 expression also enhanced mammary cancer cell motility by EGFR-mediated signaling." (PMID 21079779, 2010). "Those that also show substantial variation across the cell lines (for example, EgfR, Src, Pi3k, and Kras) may be particularly relevant in the context of breast cancer." (PMID 19317917, 2009). "Both α6β4 and EGFR are overexpressed in the basal subtype of breast cancers." (PMID 19470173, 2009). "For example, EGFR TKIs are largely inactive in colorectal cancer and breast cancer." (PMID 19088718, 2009).
breast carcinoma (continued). "Mapping of sub-networks in the EGFR-MAPK pathway in different breast cancer cell lines reveals that PAK1 may be a marker for sensitivity to MEK inhibitors." (PMID 19317917, 2009). "Targeting these receptors, to which the cancer cells have become addicted for survival, should block proliferation and either induce or sensitise the cells to apoptosis via the intrinsic pathway, thus providing the rational for using EGFR and Her2 in breast cancer therapy." (PMID 19563669, 2009). "If GEP100 also interacts with HGFR besides EGFR, about 40–80% of breast cancers may utilize the GEP100-Arf6-AMAP1 pathway, although this might not be the sole pathway for their invasion and malignancy." (PMID 19416474, 2009). "Poor response of the SqCC of the breast to chemotherapeutic regimens commonly used in breast cancer, suggests that EGFR inhibitors and platin based regimens could be a promising option for treatment of these tumors." (PMID 19829944, 2009). "While the approved use of drugs like the dual kinase inhibitor Lapatinib represents significant advances in the clinical management of breast cancer, confirmatory studies must be considered to foster the use of anti-EGFR therapies including safety, pharmacokinetics, and clinical efficacy." (PMID 19390622, 2009). "Many breast cancers overexpress Her2 (20% of all cases) and the EGFR." (PMID 19563669, 2009). "Thus, in ER-positive breast cancer cells, oestrogen is actively involved in the suppression of EGFR expression, whereas in ER-negative tumours, EGFR expression is increased." (PMID 19888222, 2009). "The race for a successful breast cancer treatmentintensified during the late 1990s and 2000s, resulting in the development ofinnovative anti-EGFR therapies in the last few years including both monoclonalantibodies (MoAbs) and small moleculetyrosine kinase inhibitors." (PMID 19390622, 2009). "It has been suggested that the frequent expression of EGFR in the absence of steroid receptors or other receptors of the EGFR family might render metaplastic breast carcinomas even more sensitive to EGFR tyrosine kinase inhibitors." (PMID 19126225, 2009). "Ofnote, HER-2/neu may also be a genetic biomarker since it has a more significantcorrelation with a selective HER-2 (+ve) population of breast cancer cases than EGFR." (PMID 19390622, 2009). "Although several growth factor receptors, such as epidermal growth factor receptor, ErbB2 and FGFR1, have been studied and implicated in breast cancer, we are only beginning to understand how these growth factor pathways interact with other autocrine or paracrine factors to promote tumourigenesis." (PMID 19393083, 2009). "First, it is important to thoroughly investigate thesignaling pathway and mechanism of EGFRto properly examine the correlation that exists between breast cancer andanomalous EGFR expression; in this case, scrutiny of the structure of EGFR andthe role it plays in cell signaling is imperative." (PMID 19390622, 2009). "Recently, a large number of non-canonical EGFR mutations were reported in both the stromal and epithelial tissue in breast cancer." (PMID 19811662, 2009). "Moreover, overexpression and amplification of EGFR in breast cancers correlates inversely with their estrogen receptor status." (PMID 19416474, 2009). "EGFR is also overexpressed in this subgroup of breast cancers, and in-vitro data suggest that crosstalk between α6β4 integrin and EGFR may be important in the progression of this basal subtype of breast cancers." (PMID 19470173, 2009). "Epidermal growth factor receptor may play a different role in endometrial cancer compared with breast cancer." (PMID 18334972, 2008). "Our data suggest that TNK2 can enhance migration and invasion of breast cancer cells via preservation of EGFR expression, notwithstanding its previously reported signalling via BCAR1, explaining its oncogenic behaviour in vitro and correlation with metastatic human breast cancer in vivo." (PMID 18435854, 2008).